PML (PML nuclear body scaffold)
Diseases named in the same sentence as PML in open-access papers (continued):
Sharing a sentence is not in itself a finding about the gene and the disease.
histiocytic lymphoma (2 papers, 2016 to 2024). "PR-9 cells were made by stably integrating a Zinc-inducible PML::RARA cDNA into the promonocyte U937 cell line, which was derived from a patient with a histiocytic lymphoma." (PMID 38648485, 2024). "Interestingly, up-regulation of PU.1 levels upon ATRA treatment has been described by Gu and colleagues in U937, a PML/RARA negative histiocytic lymphoma cell line." (PMID 27626703, 2016).
ICF syndrome (2 papers, 2018 to 2022). "The presence of HP1α has also been observed for giant PML bodies in lymphocytes of patients suffering from the ICF syndrome." (PMID 35319461, 2022). "Of note, IFN signaling was also found to be upregulated in an animal model of ICF syndrome suggesting that dual signaling via the interferon and DNA damage response may constitute a common mechanism whereby entrapment by giant PML nuclear bodies is triggered." (PMID 35319461, 2022).
kidney cancer (2 papers, 2020 to 2024). Primary or metastatic malignant neoplasm involving the kidney. "So far, the function of PML in kidney cancer has been poorly investigated, with few studies providing evidence of a tumor-suppressive role." (PMID 38730056, 2024). "The expression levels of TRIM14, PML, and TRIM21 were significantly higher in kidney cancer tissues than in normal tissues." (PMID 33173411, 2020).
liver diseases (2 papers, 2016 to 2018). "Since PML controls FAO in stem cells, it is possible that PML participates in the liver disorder by interfering the liver metabolism." (PMID 29416846, 2018).
liver fibrosis (2 papers, 2026). "Thereby, PML/BRD4 in LSECs governs inflammatory immune cell recruitment in liver fibrosis." (PMID 41842990, 2026). "In conclusion, PML/BRD4-mediated SE activation via phase separation drives proinflammatory angiocrine signaling in LSECs, initiating the inflammatory cascade and subsequent immune cell recruitment during liver fibrosis." (PMID 41842990, 2026).
lupus (2 papers, 2024). "The negative lupus panel results and persistent pancytopenia prompted further investigation, leading to the identification of Auer rods in the bone marrow biopsy, PML/RARA translocation, and the subsequent diagnosis of APML." (PMID 39050334, 2024).
malignant fibrous histiocytoma (2 papers, 2008 to 2018). "High levels of PML body expression significantly correlated with overall survival in malignant fibrous histiocytoma." (PMID 29848986, 2018).
meningioma (2 papers, 2020 to 2024). A generally slow growing tumor attached to the dura mater. "After extracting and overlapping the downregulated genes during every stage of meningioma development within three datasets, we identified 497 genes, including well-defined tumor suppressor genes PTEN, PML, EP300, and SMAD4." (PMID 37791390, 2024).
metastatic disease (2 papers, 2019 to 2023). "In the present studies, PML affected both the primary and metastatic tumor growth." (PMID 37518985, 2023).
Myocardial fibrosis (2 papers, 2021 to 2023). "Therefore, our results inferred a possible connection between TGF-β1 signaling and PML in the pathogenesis of myocardial fibrosis." (PMID 36778116, 2023). "In combination, these findings further our understanding regarding the role of PML in the pathogenesis of myocardial fibrosis and could lead the way to new therapeutic approaches and targets." (PMID 36778116, 2023). "A novel reciprocal loop of TGF-β1/PML SUMOylation/Pin1 leading to myocardial fibrosis may exist." (PMID 34128158, 2021).
Pancytopenia (2 papers, 2012 to 2024). An abnormal reduction in numbers of all blood cell types (red blood cells, white blood cells, and platelets). "Similar risk factors were not present in the presented patient, who had pancytopenia and BCR1-type PML/RARα fusion copies at presentation." (PMID 24744674, 2012).
primary biliary cholangitis (2 papers, 2020 to 2023). Primary biliary cholangitis (PBC) is a chronic and slowly progressive cholestatic liver disease of autoimmune etiology characterized by injury of the intrahepatic bile ducts that may eventually lead to liver failure. "The multiple nuclear dots pattern (AC-6) is associated with anti-Sp100, anti-MJ/NXP-2, and anti-PML, being useful in the diagnosis of diseases such as primary biliary cholangitis and autoimmune myopathy." (PMID 38283335, 2023). "Antibodies directed against PML and Sp100 are associated with primary biliary cholangitis (PBC) and the presence of these antibodies assists in the diagnosis of patients who are anti-mitochondrial antibody (AMA)-negative." (PMID 32776893, 2020).
primary effusion lymphoma (2 papers, 2018 to 2021). A large B-cell lymphoma located in the body cavities, characterized by pleural, peritoneal, and pericardial fluid lymphomatous effusions and that is always associated with human herpes virus-8 (HHV-8). "Studies in the KSHV harboring cells derived from primary effusion lymphoma (PEL) showed that PML knockout decreased the KHSV DNA replication and virion production in the reactivation, while PML overexpression enhanced the viral replication." (PMID 33546431, 2021). "In this study, we analyzed the functional influence of PML on KSHV latency and lytic replication in KSHV-infected primary effusion lymphoma (PEL) cell lines." (PMID 30349510, 2018).
renal carcinoma (2 papers, 2007 to 2020). A carcinoma arising from the epithelium of the renal parenchyma or the renal pelvis. "Seven genes (TRIM8, TRIM11, TRIM16, TRIM24, TRIM27, TRIM32, and PML) were expressed in different renal cancer cell lines through the KM expression website." (PMID 33173411, 2020).
serous ovarian cancer (2 papers, 2021 to 2024). "In high-grade serous ovarian cancers, due to the silencing of PML, ROS content, lipid peroxidation, and lysosomes, and the lysosomal Fe2+levels are reduced, which can result in potential ferroptosis and improved sensitivity to immunotherapy." (PMID 34804126, 2021).
spinocerebellar ataxia (2 papers, 2011 to 2013). "Many of these disorders are associated with expanded CAG repeats encoding polyglutamine (polyQ) tracts, including Huntington's disease and several types of spinocerebellar ataxia and PML was associated with these protein inclusions." (PMID 21304940, 2011). "Aberrant proteins generated in several neurodegenerative diseases, including Huntington's disease and spinocerebellar ataxias, accumulate in PML-NBs within neural cells and the usual nuclear distribution of PML is altered by their expression." (PMID 21304940, 2011). "Interestingly, the cytokine interferon beta, which induces PML nuclear body formation in immune cells, also appears to increase PML expression in neurons in Purkinje cells in a culture model of spinocerebellar ataxia." (PMID 24062991, 2013).
steatosis (2 papers, 2016 to 2024). Increased lipid within the cytoplasm of cells. "Additionally, CHB-associated deficiency of PML (promyelocytic leukemia protein) results in altered lipid metabolism and steatosis-associated carcinogenesis." (PMID 38251375, 2024). "PML−/− mice exhibited somatic mutations in DNA repair genes and developed severe steatosis and proliferative disorders, but not HCC." (PMID 27058621, 2016). "Based on our finding that PML−/− mice did not develop HCC, but did develop severe steatosis and proliferative disorders in multiple organs throughout their lifetime, a predisposition for mutations in DNA repair genes did not appear to be a prerequisite for HCC initiation." (PMID 27058621, 2016).
vitiligo (2 papers, 2013 to 2025). Generalized well circumscribed patches of leukoderma that are generally distributed over symmetric body locations and is due to autoimmune destruction of melanocytes. "In healthy sample PML was weakly detected only in the cytoplasm of upper epidermal layers whereas in vitiligo biopsies a strong citoplasmic signal was associated with an intense nuclear positivity of all epidermal layers." (PMID 23555779, 2013).
acute megakaryoblastic leukemia (1 paper, 2013). Acute megakaryoblastic leukemia (AMKL) is a form of acute myeloid leukemia (AML) that occurs predominantly in childhood and particularly in children with Down syndrome (DS-AMKL). "In particular, miR-125 overexpression was identified in different AML subtypes characterized by specific chromosomal abnormalities, including AML1/ETO, PML/RARα and FLT3 translocations, and in Down Syndrome-associated acute megakaryoblastic leukemia (AMKL)." (PMID 24145746, 2013).
age (1 paper, 2024). A temporal measurement of the time period elapsed since an identifiable point in the life cycle of an organism. "The findings confirm the significant role of PML-NBs in cellular aging processes and open new avenues for investigating senescence mechanisms and age-associated diseases." (PMID 39768166, 2024).
AIDS (1 paper, 2016). A syndrome resulting from the acquired deficiency of cellular immunity caused by the human immunodeficiency virus (HIV). "The availability of PML knockout mice for crossing experiments might finally open the door to the long sought-after human tissue-free murine model for AIDS." (PMID 27000403, 2016).
alpha thalassemia/mental retardation syndrome X-linked (1 paper, 2021). "IFI16 forms filamentous structures on HSV DNA that recruit components of PML-NB including PML, speckled 100 kDa (SP100) and alpha thalassemia/mental retardation syndrome X-linked (ATRX), to increase repression of viral gene expression." (PMID 34676800, 2021).
Alzheimer disease (1 paper, 2019). A progressive, neurodegenerative disease characterized by loss of function and death of nerve cells in several areas of the brain leading to loss of cognitive function such as memory and language. "KLHL20 is a related CUL3-dependent ubiquitin ligase linked to autophagy, cancer, and Alzheimer's disease that promotes the ubiquitination and degradation of substrates including DAPK1, PML, and ULK1." (PMID 31279627, 2019).
Aortic dissection (1 paper, 2022). Aortic dissection refers to a tear in the intimal layer of the aorta causing a separation between the intima and the medial layers of the aorta. "New genes (MLX, DAB2IP, EP300, ZFYVE9, PML, PRKCD) were suggested as candidate aortic dissection-associated genes, through correlation analyses performed on the results of a WES study on a cohort of 99 Chinese cases." (PMID 35892496, 2022).
autoimmune polyendocrine syndrome type 1 (1 paper, 2020). Autoimmune polyendocrinopathy type 1, or APECED syndrome, is a genetic disease that manifests in childhood or early adolescence with a combination of chronic mucocutaneous candidiasis, hypoparathyroidism and autoimmune adrenal failure. "Several loss-of-function Aire mutants, including those causing autoimmune polyendocrine syndrome type-1, form foci with increased PML body association." (PMID 32242017, 2020).
bacteremia (1 paper, 2018). "This immune complex contributes to the evasion of PML-mediated phagocytic clearance, which is central to the establishment of bacteremia caused by SS2." (PMID 29973920, 2018).
benign prostatic hyperplasia (1 paper, 2013). A non-cancerous nodular enlargement of the prostate gland. "Similarly, and in contrast to what was observed in benign prostatic hyperplasia, no increase in PML or PML-IV were observed." (PMID 24171943, 2013).
Bloom syndrome (1 paper, 2013). Bloom syndrome (BSyn) is a rare chromosomal breakage syndrome characterized by a marked genetic instability associated with pre- and postnatal growth retardation, facial sun-sensitive telangiectatic erythema, increased susceptibility to infections, and predisposition to cancer. "Indeed, Pml−/− MEFs show a greatly augmented frequency of sister chromatid exchange (SCE) which is a distinctive molecular feature of Bloom syndrome cell genomic instability, suggesting that the localization of BLM to PML-NB is important to ensure BLM proper function." (PMID 23847764, 2013).
Cerebral ischemia (1 paper, 2016). Restriction of arterial blood supply to the brain associated with insufficient oxygenation to support the metabolic requirements of the tissue. "To investigate a potential role of PML in protection and regeneration of tissue after injury, we induced cerebral ischemia by permanent occlusion of the left common carotid artery followed by systemic hypoxia in wild-type and PML-depleted mice at postnatal day 9 (P9)." (PMID 27468695, 2016).
common variable immunodeficiency (1 paper, 2025). "We also note that, like IEI in general, there is extensive genetic and phenotypic heterogeneity reported for IEI plus PML genes, with many (21 of 26, 81%) linked to the broader category of common variable immunodeficiency (CVID)." (PMID 40761639, 2025).
Crohn disease (1 paper, 2025). A gastrointestinal disorder characterized by chronic inflammation involving all layers of the intestinal wall, noncaseating granulomas affecting the intestinal wall and regional lymph nodes, and transmural fibrosis. "Pro-inflammatory cytokines such as TNF-α and IFN-α upregulate PML expression in intestinal tissues of IBD patients, especially in Crohn’s disease." (PMID 41312366, 2025).
E. coli infection (1 paper, 2013). "Hence the pro-senescent phenotype accompanied with the persistent DNA- damage induced by pks+ E. coli infection is linked with enhanced SAHF and PML-NBs formation." (PMID 24116215, 2013).
Epstein-Barr virus infection (1 paper, 2013). An infection that is caused by Epstein-Barr virus. "A similar competition for constant levels of SUMO regulates Epstein-Barr virus infections, where the viral BZLF protein competes with the host PML protein for limiting amounts of SUMO1." (PMID 24348269, 2013).
Erythema (1 paper, 2020). Redness of the skin, caused by hyperemia of the capillaries in the lower layers of the skin. "Upon challenge of primed mice for 4 hr with fixed S. aureus, we observed significantly more skin-infiltrating PML and Ly6Chi Mφ and visible skin erythema in previously infected mice." (PMID 32639232, 2020).
fibrosarcoma (1 paper, 2019). A malignant mesenchymal fibroblastic neoplasm affecting the soft tissue and bone. "To determine if the relationship between ATRX and PML expression is causal, we depleted ATRX in HT1080 fibrosarcoma cells using siRNA treatment and examined PML protein expression." (PMID 30745338, 2019).
fibrosis (1 paper, 2023). the formation of excess fibrous connective tissue in an organ or tissue in a reparative or reactive process. "However, the molecular and signaling mechanism of PML in cardiac fibrosis are still unclear." (PMID 36778116, 2023).
hepatocellular adenoma (1 paper, 2016). A benign epithelial neoplasm arising from the hepatocytes. "The HBsAg transgene, but not the PML deletion, induced HCC and/or hepatocellular adenoma (HCA) and As2O3 treatment significantly increased hepatocyte death while decreasing HCC development only in PML+/+HBsAgtg/0 mice." (PMID 27058621, 2016).
Huntington disease (1 paper, 2011). Huntington disease (HD) is a rare neurodegenerative disorder of the central nervous system characterized by unwanted choreatic movements, behavioral and psychiatric disturbances and dementia. "Similar PML nuclear bodies that sequester abnormal proteins have been reported in neurodegenerative disorders, like Huntington's disease." (PMID 21304940, 2011).
Hypoalbuminemia (1 paper, 2021). The concentration of albumin in the blood circulation is below the lower limit of normal. "Previous studies reported that these factors increased the risk of APL thrombosis, including male, high score performance status (PS), high white blood cell count and platelet count, low fibrinogen levels, hypoalbuminemia, PML/RARa fusion gene variant, CD2/CD15 and FLT3-ITD positive." (PMID 34130694, 2021).
influenza (1 paper, 2021). An acute viral infection of the respiratory tract, occurring in isolated cases, in epidemics, or in pandemics; it is caused by serologically different strains of viruses (influenzaviruses) designated A, B, and C, has a 3-day incubation period, and usually lasts for 3 to 10 days. "However, neither the mechanism by which PML exerts anti-influenza activity nor the significance of PML NB recruitment of viral proteins (the matrix protein M1 and the nonstructural polypeptides NS1 and NS2) has been addressed yet." (PMID 34513832, 2021).
Insulin resistance (1 paper, 2020). Increased resistance towards insulin, that is, diminished effectiveness of insulin in reducing blood glucose levels. "Our results confirm previous findings on PML regulation modulated by TNFα, and may suggest a role of PML in insulin resistance." (PMID 33257747, 2020).
intestinal tumours (1 paper, 2020). "Low PML expression in intestinal tumours was further validated by immunohistochemistry (IHC) on an independent cohort of 156 GIST cases (15 intestinal, 128 stomach, and 13 other), which identified all intestinal GIST cases as PML negative." (PMID 31722230, 2020).
ischemia (1 paper, 2021). A hypoperfusion of the BLOOD through an organ or tissue caused by a PATHOLOGIC CONSTRICTION or obstruction of its BLOOD VESSELS, or an absence of BLOOD CIRCULATION.
keloid (1 paper, 2019). An irregularly shaped, elevated mark on the skin caused by deposits of excessive amounts of collagen during wound healing. "Interestingly, elevated levels of tumor suppressors such as PML are also seen in the hypercellular regions of keloids, suggesting senescence as a factor which confers keloids their benign nature." (PMID 31440236, 2019).
leukopenia (1 paper, 2024). "PML-deficient mice show immune system phenotypes such as leukopenia and reduced innate immunity, but no reproductive phenotypes have been reported, suggesting that PML plays an auxiliary role in reproduction." (PMID 39201340, 2024).
lipid metabolism disorder (1 paper, 2020). "Serum TG, HDL, and LDL levels were higher in 3- to 4-month-old Pml-RarαKI mice (no APL symptoms) than in wild-type (WT) mice of the same age, indicating that PML-RARα plays a critical role in the lipid metabolism disorder associated with APL." (PMID 32929351, 2020).
liver cancer (1 paper, 2019). An epithelial or non-epithelial malignant neoplasm that arises from the liver.
liver steatosis (1 paper, 2022). "Carracedo and Pandolf reported increased hepatic PML protein levels during liver steatosis." (PMID 35406736, 2022).